EGR1 (early growth response 1)
Diseases named in the same sentence as EGR1 in open-access papers (continued):
Sharing a sentence is not in itself a finding about the gene and the disease.
tumor (continued). "Functional study had showed that over-expression of CBX8 promoted tumor growth and metastasis by increasing EGR1 and miR-365-3p to stimulate the AKT/β-catenin pathway, while CBX8 inhibition suppressed these effects." (PMID 30481161, 2018). "Intriguingly, EGR1 can function as a tumor suppressor or an oncogene, depending on the type of tumor cells." (PMID 29246166, 2017). "We have previously shown that SS18-SSX interacts with its partners at promoters recognized by ATF2, repressing transcription at critical tumor suppressor loci including EGR1 and CDKN2A." (PMID 28056055, 2017). "First, Egr-1 is involved in G-1 induced signaling in different tumor cells; second, Egr-1 has a dichotomic function since it can work as oncogene but also as tumor suppressor." (PMID 29383185, 2017). "Similar to other critical tumor suppressors like Pten and Msr1, it was observed that Egr1 expression is down-regulated by BCR-ABL both in vitro as well as in vivo." (PMID 29050203, 2017). "Collectively, these studies have demonstrated that Egr1 functions as a tumor suppressor in HCC via inhibiting tumor proliferation and promoting apoptosis." (PMID 29607419, 2017). "Another study has demonstrated that Egr1 can also behave as a tumor suppressor in AML1-ETO-positive AML." (PMID 29050203, 2017). "These novel findings on the tumor suppressor role of Egr1 in CML provide the impetus to study the effect of altering Egr1 expression in AML, where the overall five year survival rate remains low." (PMID 29050203, 2017). "It targets the tumour suppressors—early growth response protein 1 (EGR1) and phosphatase and tensin homolog (PTEN)—and blocks their translation." (PMID 28895916, 2017). "These include EGR1, which is known to bind to the ZFP36 promotor and regulate a number of factors associated with tumor progression in mammary gland tumors, including FOS." (PMID 29073243, 2017). "EGR-1 is a point of convergence of many intracellular signaling cascades that control tumor cell growth and proliferation as well as others that relate to cell death machinery." (PMID 29383185, 2017). "Xenograft mouse model of U251 cells and U251SLCs was used to investigate the role of EGR1 on tumor growth in vivo." (PMID 29246166, 2017). "Inhibition of miR-183-5p and miR-182-5p in vitro causes up-regulation of the tumor-suppressive genes CBX7 and EGR1." (PMID 29141042, 2017). "For example, using multicellular tumor spheroids, it has been shown that EGR-1 overexpression makes tumor cells more sensitive to necrosis induced by glucose depletion, and blocking EGR-1 with a shRNA suppresses growth of the tumorspheres." (PMID 28758926, 2017). "Inhibition of P42/44MAPK in HepG2 cells leads to suppression on cell growth, proliferation, and survival, accompanied by an induction of Egr1 in tumor cells." (PMID 29607419, 2017). "Given the evidence that Egr1 has tumor suppressor functions, we wanted to assess how its expression is regulated by the BCR-ABL oncogene." (PMID 29050203, 2017). "EGR1 is an immediate-early gene induced by estrogen, growth factors, or stress signals, and can exhibit both tumor suppressor and promoter activities." (PMID 29228577, 2017). "On the other hand, EGR1 also exhibits a tumor suppressor function by mainly inducing tumor cell apoptosis in other types of cancers." (PMID 27442508, 2016). "In contrast to the SKOV3ip1-EV tumours where miR-192 treatment resulted in a 90% reduction in tumour burden, only 65 and 30% reduction in tumour burden was observed for tumours expressing EGR1 and HOXB9, respectively." (PMID 27041221, 2016). "EGR1 has been shown to accelerate tumor growth and progression by mainly inducing cell proliferation, angiogenesis, and invasion in gastric, ovarian, prostate, and liver cancers." (PMID 27442508, 2016).
tumor (continued). "In CRC, EGR1 is elevated in tumors when compared to matched normal tissues and enhances tumor cell proliferation." (PMID 27442508, 2016). "In rat tumor xenograft models, resveratrol induced the Egr-1 expression from its chromosomal locus [Egr-1 promoter CC(A + T) rich GG sequences], showing anticancer response with the increase of TNF-α." (PMID 27148534, 2016). "Both TTP and EGR1 were significantly downregulated in 90% of tumor tissues compared to normal tissue (EGR1: p = 0.0277; TTP: p = 0.0065)." (PMID 26343742, 2015). "EGR1 is a tumor suppressor and is regulated by many different stimuli such as cytokines, growth factors, and apoptosis-promoting factors." (PMID 26461477, 2015). "In this regard, it has been demonstrated that GPER agonists upregulate the expression of genes associated with tumor progression like c-fos, cyclins A, D1, and E, the connective tissue growth factor (CTGF), and the early growth response-1 (Egr-1)." (PMID 25798130, 2015). "We have developed a baculovirus dual expression vector which contains the NIS gene under the control of a tumor-specific promoter, hTERT, and the K5 gene driven by a radiation-inducible promoter, Egr1." (PMID 24647588, 2014). "Here, in our research, Egr-1 performs as a tumor suppressor and leads to cell growth arrest and apoptosis via ERK and JNK in arsenic treated BEAS-2B cells." (PMID 25004251, 2014). "Several studies suggest that EGR1 can act as a tumour suppressor gene, being able to suppress the growth of several kind of carcinoma cells." (PMID 24865347, 2014). "This prompted us to investigate EGR1 protein expression in our tumor samples which showed low-level variable nuclear reactivity in all stained samples, including 47 control samples of possible mimickers of SFT." (PMID 25432794, 2014). "Most of known Egr-1 targets are genes involved in tumor metastasis, such as plasminogen activator inhibitor-1 (PAI-1), Transforming Growth Factor-beta 1 (TGF-β1), and matrix metalloporteinase-9 (MMP-9)." (PMID 25004251, 2014). "Within the tumor tissue, endothelial cells, cancer cells, fibroblasts, and tumor-infiltrating macrophages can express Egr-1." (PMID 25502753, 2014). "In this regard, several studies have reported that Egr-1 expression in cancer cells, endothelial cells, and macrophages is related to tumor progression." (PMID 25502753, 2014). "Egr-1 exhibits either oncogenic or tumor suppressive properties depending on the type of cells and stimuli." (PMID 25004251, 2014). "The transcription factor EGR1 is a regulator of multiple tumor suppressors but, paradoxically, can also promote tumor progression." (PMID 24058270, 2013). "In one such study, that is perhaps the most similar to ours, a plasmid in which the expression of IL-12 was controlled by the inducible Egr1 promoter was used in the B16 murine tumor model." (PMID 24219565, 2013). "Although cell motility and/or EGR-1 are likely to be important in tumor progression, it is logical to assume that their relative importance is tumor and context dependent." (PMID 23658821, 2013). "We found that Egr-1 shRNA prevented necrosis, whereas Egr-1 overexpression made tumour cells more sensitive to GD, thereby leading to necrosis." (PMID 23152075, 2013). "Egr-1 is induced by a number of different stimuli, such as anti-cancer drugs and growth factors and inhibits or stimulates tumour growth depending the cellular context and the duration of Egr-1 induction." (PMID 23152075, 2013). "Taken together, these results demonstrate that Egr-1 plays an important role(s) in GD-induced necrosis and tumour progression." (PMID 23152075, 2013).
tumor (continued). "We evaluated that the estrogen dependent activation of miR-191/425 induces proliferation in part by targeting the estrogen modulated tumor-suppressor gene, EGR1." (PMID 23505378, 2013). "Necrosis-inhibiting activity of Egr-1 shRNA was also seen in multicellular tumour spheroids (MTSs), an in vitro tumour model system." (PMID 23152075, 2013). "Studies of tumor cells and T lymphocytes have shown that heparanase expression can be induced by the transcription factor early growth response 1 (EGR1) which, itself, is dependent on ERK1/2 activity." (PMID 23300607, 2012). "Egr1 is known to play various roles such as tumor promotion in prostate, tumor suppressor in various cancers, cell growth and differentiation and hematopoietic cell maturation." (PMID 23209659, 2012). "Overexpression of EGR1 has been reported to increase proliferation, enhance tumor growth and antagonize the effects of the tumor suppressor Wilms tumor 1 (WT1) in baby rat kidney cells." (PMID 23029358, 2012). "Plag1 and Egr1 gene transcript levels were assessed by realtime quantitative PCR with cDNA extracted from CD44hi and CD44neg tumor cells." (PMID 21858056, 2011). "Two of these, CBX7 and EGR1, have well-described tumor suppressor functions, and recently DOK4 family members (DOK1, DOK2, and DOK3) were identified as lung tumor suppressors." (PMID 21375733, 2011). "Our data showed that both Plag1and Egr1 gene transcriptions were upregulated in murine salivary gland CD44hi tumor cells compared to CD44neg cells." (PMID 21858056, 2011). "Several investigations have shown that EGR1 plays an important role in the control of tumor metastasis through regulation of cancer invasion-related genes, including TGF-β1, thrombospondin-1, and plasminogen activator inhibitor-1." (PMID 21283769, 2011). "EGR1 can be rapidly induced by many stimuli, including growth factors, cytokines, ultraviolet light, anti-tumour agents, and various stresses [8,10,24, Cao, 1992 #88,25,28–35]." (PMID 21283769, 2011). "To examine the effects of anti-tumour agents on EGR1 expression, we performed real-time PCR after anti-tumour agent treatment." (PMID 21283769, 2011). "It has been reported that EGR1 over-expression suppresses the growth of cell in soft agar and tumor growth in nude mice." (PMID 21283769, 2011). "Further, we examined which signaling pathway promotes EGR1 expression following anti-tumor agent treatment." (PMID 21283769, 2011). "EGR1 is also observed to be required for differentiation and apoptosis in normal and tumor cells; on the basis of these observations, it seems that EGR1 lies at a convergence point and its effects depend on the signals transduced and on the cell context." (PMID 21998680, 2011). "To date, the studies analysing the functions of Egr-1 have been contradictory, with reports of both cytoprotective and pro-apoptotic functions in tumour cells." (PMID 20087343, 2010). "Within the top 20 genes ranked by Notch pathway-guided COCA, there are several genes related to differentiation (Tdgf1, Egr1 and Lefty1), cell growth (Ddit4, Hk2, Phlda2, Egln3 and Igfbp1) and tumor/cancer development (Afp, Sfrp2, Egr1, Hk2 and Phlda2)." (PMID 20353603, 2010).
tumor (continued). "Another study linked Egr-1 to TRAIL that showed that TNF and TRAIL are released from irradiated (IR) tumour cells and induce bystander death of neighbouring/IR-unaffected cells." (PMID 20087343, 2010). "This study also indicates that during irradiation or genotoxic drug exposure, Egr-1 enhances tumour regression by inducing a bystander effect." (PMID 20087343, 2010). "We also showed that the ectopic production of nerve growth factor (NGF) in the melanoma tumor tissue as a tumor-released mediator can induce expression of the TF Egr-1 in the salivary gland." (PMID 19517020, 2009). "EGR1 has been shown to mediate apoptosis in a number of malignancies, possibly by activating the transcription of pro-apoptotic genes such as PTEN, and EGR1 can also block angiogenesis and tumour invasion." (PMID 19156136, 2009). "Overexpression of Egr-1 delivered via adenovirus resulted in reduced tumor growth and diminished expression of angiogenic factors in a mouse model." (PMID 19200397, 2009). "Stage T1 tumors exhibited significantly higher frequencies of tumor cells with nuclear Egr-1 immunolabelling than Ta tumors (P = 0.001)." (PMID 19878561, 2009). "Mice deficient in Egr-1 exhibit reduced growth of LLC1 tumors, and this phenomenon is associated with overexpression of Mig locally within the tumor." (PMID 19200397, 2009). "In our study, 5-FU was employed to activate the Egr-1 promoter in human bone marrow stromal cells injected into tumor-bearing mice, resulting in exogenous FL expression." (PMID 19765320, 2009). "In the univariate analysis Egr-1, patient age, tumor type, tumor stage and tumor grade showed a significant association with progression to T2-T4." (PMID 19878561, 2009). "Tumor cells with nuclear Egr-1 immunolabelling were found to localize at the tumor front in some of the tumor biopsies." (PMID 19878561, 2009). "The associations between patient age, sex, stage, grade, tumor size, treatment, concomitant CIS, tumor type and Egr-1 protein expression with progression to T2-T4 invasive tumors were tested by univariate Cox regression analysis." (PMID 19878561, 2009). "Gene therapy using expression of the tumor necrosis factor regulated by the Egr-1 promoter has already been used in humans for tumor therapy." (PMID 19765320, 2009). "When the gene expression was blocked with an EGR1 siRNA, Burkitt's cells proliferated more than normal cells, supporting the tumor suppressor role of EGR-1 in Burkitt's cells." (PMID 19674465, 2009). "We found that Egr-1 expression was correlated to tumor stage, stage T1 tumors exhibited significantly higher levels of Egr-1 positive tumor cells than Ta tumors (P = 0.001, Mann Whitney test)." (PMID 19878561, 2009). "Finally, spatial transcriptome analysis of adrenal cryosections also demonstrated downregulation of EGR1 gene expression in APA tumor regions compared to the adjacent zona glomerulosa in six PA adrenal samples." (PMID 39826326, 2025). "Notably, Egr1 emerged as a strong tumor suppressor and its knockout resulted in approximately a fivefold increase in tumor size at 20 weeks (two-sample t-test, p < 0.05), exceeding the impact observed with Rb1 loss." (PMID 41705258, 2025). "Notably, EGR1‐high tumours (MP7‐dominant) exhibited strong enrichment of the CAF marker FAP and a striking absence of CD8 T cell infiltration." (PMID 40292733, 2025).
tumor (continued). "Furthermore, genes associated with proliferation and survival, including CD69, EGR1 (early growth response protein 1), and PIM2 (proviral integrations of moloney virus 2), were increased, suggesting a potential role in tumor progression." (PMID 40809351, 2025). "By contrast, the nuclear EGR1 level was significantly lower in tumor tissues." (PMID 40124511, 2025). "Moreover, EGR1 promotes angiogenesis in other cancer types, further underscoring its multifaceted role in tumor progression." (PMID 40519297, 2025). "Recent findings reveal that EGR1 plays different regulatory roles in various tumor tissues, accelerating tumor development and expansion by enhancing cell proliferation, angiogenesis, and invasion, while also demonstrating cancer-inhibiting properties and inducing apoptosis in tumor cells." (PMID 39866235, 2025). "The expression of EGR1 in prostate cancer tissues is greater than that in the surrounding tissues; moreover, its expression level is positively correlated with the degree of tumour malignancy." (PMID 40936205, 2025). "While the full MAC assembly can cause cell lysis, sub-lytic MAC deposition—facilitated by elevated C7—activates intracellular pathways in tumor cells, including Ca2+- and G-protein-mediated signals, and transcription factors such as EGR1, IRF1, AREG, and CXCL1." (PMID 40806542, 2025). "We also note the proapoptotic protein PMAIP1 (NOXA) that was downregulated in the drug-adapted tumors, and transcription factors NFIX, EGR1, and HES2 implicated in tumor promotion or suppression, which were differentially affected by LT everolimus and the drug combination." (PMID 39541354, 2024). "The activation process of PZCT is controlled by a tumor-specific bioreciprocal mechanism overexpressing miR-21, which utilizes the catalytic action of Zn2+ to generate a large amount of DNAzymes, silencing EGR-1 mRNA, and thereby inhibiting tumor growth." (PMID 38607182, 2024). "Our findings suggest that EGR1 possesses therapeutic potential as a tumor suppressor gene in HCC, and that EGR1 gene therapy may offer benefits for HCC patients." (PMID 38287371, 2024). "However, the role of EGR1 derived from the tumor microenvironment in reshaping the phenotypes of GC cells and its specific molecular mechanisms in increasing the potential for PM are still unclear." (PMID 38385088, 2024). "Moreover, in a mouse model of HCC induced by DEN/CCL4, AAV-mediated EGR1 gene therapy exhibited the suppression of tumor growth and alleviation of liver injury." (PMID 38287371, 2024). "These biocapsulated DNAzymes suppressed EGR1 levels in tumors and induced tumor cell death." (PMID 39619154, 2024). "After thirty days, the tumor samples were harvested and EGR1 attenuated tumor growth." (PMID 38287371, 2024). "Through a literature review, it was found that the function of EGR1 as a tumor suppressor gene mostly depends on the transcription of PTEN as a transcription factor to exert its tumor suppressor function, and the JASPAR database also showed that PTEN was the target of EGR1." (PMID 39044249, 2024). "EGR1 is involved in tumor cell proliferation, invasion and metastasis, and tumor angiogenesis." (PMID 38324544, 2024). "Simultaneously, GSH in tumor cells would reduce MnO2 into Mn2+, thus activating the DNAzyme and enhancing the cleavage activity of DNAzyme on Egr-1 mRNA, which would down-regulate Egr-1 protein in tumor cells and achieve gene therapy." (PMID 36975688, 2023). "Through public data and experimental verification, we found that inhibiting the expression of EGR1 can regulate the invasion of tumour cells, and the decreased expression of EGR1 significantly upregulated the expression of E-cadherin and downregulated the targeted genes FAS and HSPG2." (PMID 37817210, 2023). "Among them CCNB1, MIF, PLA2G4A may be regarded as oncogenes, whereas RNASE3, APOE, FOXO1, KIT, and EGR1 may be tumor suppressor genes." (PMID 37065484, 2023).